EGFR (epidermal growth factor receptor)
Diseases named in the same sentence as EGFR in open-access papers (continued):
Sharing a sentence is not in itself a finding about the gene and the disease.
breast carcinoma (continued). "Combined blockade of ANO1 and EGFR remarkably improved response to cetuximab in HNSCC and breast cancer." (PMID 40396170, 2025). "In breast cancer, the Top 5 genes were MYC, EGFR, SRC, HSP90AB1, PXDNL, and the Top 4 genes are CGC drivers." (PMID 40478912, 2025). "Of note, the ERβ/EGFR/IGF‐IR crosstalk and ERβ/JAK/STAT signaling pathway significantly influence critical breast cancer cell functional properties, such as invasion and migration." (PMID 39285617, 2025). "Representing 15–20% of breast cancer cases, TNBC exhibits intrinsic resistant against targeted therapeutics for epidermal growth factor receptor (EGFR) and MET, despite their frequent amplification in TNBC." (PMID 40649917, 2025). "This EGFR transactivation initiates downstream signaling pathways, including MAPK/ERK1/2 and PI3K/Akt, promoting breast cancer cell survival and proliferation." (PMID 40641933, 2025). "As a result, EGFR-TKIs have emerged as a key therapeutic strategy in both NSCLC and certain breast cancer subtypes." (PMID 40006082, 2025). "Other FASN inhibitors, including C75, EGFR, Fasnall, and TVB-3166, also demonstrate significant inhibitory effects on breast cancer, although they face limitations in clinical application." (PMID 40002245, 2025). "Once released, this extracellular domain binds to the epidermal growth factor receptor (EGFR), activating signaling pathways that enhance the migratory and invasive potential of breast cancer cells, leading to metastasis." (PMID 40813760, 2025). "Other studies have also shown that combinations of panobinostat with an EGFR inhibitor suppressed claudin-low (CL) TNBC cell proliferation, proposing class I HDACs as therapeutic targets for breast cancer patients with TNBC." (PMID 39008483, 2024). "Previous reports indicate that MIR539 expression is downregulated in breast cancer tissues and cell lines, and MIR539 acts as a tumor suppressor by targeting epidermal growth factor receptor, specificity protein 1, or laminin subunit alpha 4 expression." (PMID 39145770, 2024). "SDC1 participates in establishing a permissive lung microenvironment for breast cancer metastasis, while SDC4 engages with EGFR to sustain cell cycle progression in head and neck carcinoma." (PMID 38546390, 2024). "The anti-EGFR-MPB nanocomposite represents a significant advancement in precision cancer therapy, particularly for breast cancer treatment." (PMID 39525484, 2024). "First, we characterized the molecular interaction of EGFR and HER2 in the membrane of SK-BR-3 mammary carcinoma cells that express these receptors at low and high levels (~80,000 and 800,000 per cell, respectively)." (PMID 38892166, 2024). "Three essential core genes—EGFR, BCL2, and MAPK3—in the PPI network of breast cancer-related targets of SP were among the top ten genes." (PMID 39057437, 2024). "In breast cancer, the transmembrane MUC1‐C‐terminal subunit (MUC1‐C) interacts with EGFR, ErbB2, and other receptor tyrosine kinases and contributes to the activation of the PI3K→AKT and MEK→ERK pathways." (PMID 38778448, 2024). "For instance, suppression of SHIP2 promotes cell proliferation and metastasis by interacting with c-cbl and influencing epidermal growth factor receptor (EGFR) turnover, thereby enhancing EGF-induced Akt activation in breast cancer." (PMID 38200519, 2024). "These agents have specific targets in various types of cancer, such as blocking Bruton’s tyrosine kinase (BTK) in mantle cell lymphoma, targeting mutant EGFR in NSCLC, or inhibiting ErbB2 in HER2-positive breast cancer, and Waldenström macroglobulinemia." (PMID 39404419, 2024). "Lapatinib, a reversible tyrosine kinase inhibitor (TKI) to HER2 and Epidermal Growth Factor Receptor (EGFR), is currently approved for use in HER2-positive breast cancer patients after progression on a trastuzumab containing regimen." (PMID 38600326, 2024).
breast carcinoma (continued). "As aberrant expression of EGFR and MUC1 has been reported in various epithelial tumors, we carried out IHC experiments on LUAD, CRC and breast cancer tissues." (PMID 39664199, 2024). "The epidermal growth factor receptor (EGFR) family, including ErbB4, plays critical roles in various cancers, notably breast cancer (BC)." (PMID 39949609, 2024). "In this study, novel rhodanine–piperazine hybrids were designed and synthesized as potential inhibitors of VEGFR, EGFR, and HER2 tyrosine kinases, with the aim of developing new anticancer agents targeting breast cancer." (PMID 39596465, 2024). "Downstream of EGFR s-nitrosation, oncogenic signaling pathways, including c-Myc, Akt, STAT3, and β-catenin, are activated in breast cancer." (PMID 38601214, 2024). "Based on this scenario, various studies have shown that ALA can target ERBB1/EGFR to exert anticancer effects in cancer types such as thyroid cancer and breast cancer, primarily by inhibiting the generation and release of downstream effectors." (PMID 39199143, 2024). "This is consistent with previous studies on breast cancer, showing that MUC1 influences cell proliferation by inducing EGF receptor (EGFR) nuclear translocation and increasing its binding affinity with the cyclin D1 gene promoter." (PMID 38254882, 2024). "Certain targets were enriched in specific cancer types as expected based on the clinical treatment landscape or tumor biology (eg, EGFR, MET, ROS1, MET, and ALK in NSCLC; or ERBB2, CDK4, CDK6, aromatase, and ER in breast cancer)." (PMID 37682776, 2024). "In this study, we identified the role of SUSD2 in the prognostic aspect and verified how SUSD2 is regulated in EGFR+ and/or HER2+ breast cancer." (PMID 39791720, 2024). "EGFR/AKT signaling pathway is thought to be involved in the development and development of various malignant tumors, including breast cancer and glioblastoma." (PMID 39075515, 2024). "The decrease in E-cadherin and epidermal growth factor receptor (EGFR) signal and expression is related to decreasing in breast cancer cells activity, adhesion, migration and invasion." (PMID 38586328, 2024). "Our findings suggest the clinical significance of SUSD2 as a biomarker for EGFR+ HER2+ breast cancer and highlight the use of STAT3-specific inhibitors for treating EGFR+ HER2+ breast cancer expressing SUSD2." (PMID 39791720, 2024). "The transcript expressions of CTSD, EGFR, CNND1, and BCL2 in breast cancer patients can be observed in the box plots." (PMID 39202273, 2024). "Similar results were obtained when examining the co-expression of PTGS2/ESR2/EGFR/JUN/and MMP2 genes’ signature in breast cancer cell lines representative of different molecular subtypes." (PMID 39707884, 2024). "TIMER2.0 was used to estimate the correlations between ESR1, with a purity adjustment, and the expression of CTSD, EGFR, CCND1, and BCL2 in breast cancer subtypes." (PMID 39202273, 2024). "Epertinib (S-222611) is a reversible inhibitor of HER2, EGFR and HER4, that demonstrated more potent effect compared to lapatinib, as well as antitumor activity in a brain metastasis model of HER-positive breast cancer in preclinical studies." (PMID 38256137, 2024). "TNBCs, the basal subtype of breast cancer, which is highly metastatic due to the presence of CD24−/CD44+‐breast CSCs, often express epidermal growth factor receptor (EGFR) in high levels, which serve as a biomarker." (PMID 38522013, 2024). "The downregulation of Epidermal Growth Factor Receptor (EGFR) and Proline, Glutamic Acid, and Leucine Rich Protein 1 (PELP1) can reduce hormone resistance in breast cancer cells to therapy." (PMID 39199245, 2024). "One of the main signaling pathways of EGFR activation is the activation of AKT serine-threonine kinases, which leads to the induction of proliferation, growth and inhibition of apoptosis in breast cancer." (PMID 38706904, 2024).
breast carcinoma (continued). "The epidermal growth factor receptor (EGFR) is overexpressed in several tumors of epithelial origin, including breast cancer." (PMID 38460941, 2024). "Other antibodies, such as Cetuximab(anti-EGFR), Pertuzumab(anti-HER2), and bispecific antibodies-Catumaxomab, have opened new avenues in clinical research for gastrointestinal and breast cancer treatments." (PMID 38840908, 2024). "To explore the effect of EGFR and/or HER2 expression in breast cancer, we performed a cDNA microarray." (PMID 39791720, 2024). "MiR-133a has emerged as a tumor suppressor in non-small cell lung cancer (NSCLC), esophageal cancer (EC), prostate cancer (PC) and breast cancer (BC), targeting genes such as SOX4, EGFR, FSCN1, and COL1A1." (PMID 38504785, 2024). "In breast cancer, ectopic expression of MPP7 promotes cell migration and invasion by modulating epithelial–mesenchymal transition and activating the epidermal growth factor receptor signaling." (PMID 39224268, 2024). "In MDA-MB-231 breast cancer cells, EGF induces an increase in levels of ICAM-1, while the EGFR inhibitor reduces ICAM-1 expression." (PMID 39594667, 2024). "One analysis of primary breast cancer samples revealed that ERBB2, FGFR1, MYC, CCND1, and PIK3CA were commonly amplified, and other well-known oncogenes such as CCND2, EGFR, FGFR2, and NOTCH3 were amplified at lower frequencies." (PMID 38611020, 2024). "Previous studies have confirmed that HER2/EGFR activity is essential for the TGFβ-stimulated migration of breast cancer cells, while the inhibition of HER2/EGFR activity can enhance the inhibitory effects of TGFβ on cellular processes." (PMID 39769140, 2024). "Among three major subtypes based on hormone receptor and epidermal growth factor receptor status, HR+/HER2- breast cancer is the most common subtype, accounting for one-third of all breast cancers." (PMID 38375194, 2024). "Cluster 2#: The role of HER2 gene in breast cancer and the effect of anti-HER2/EGFR-TKI drugs in the treatment of HER2-positive breast cancer." (PMID 38894873, 2024). "TAMs enhance tumor progression by releasing growth factors, such as epidermal growth factor receptor (EGFR), which result in breast cancer proliferation." (PMID 39309874, 2024). "The tumor xenograft models used in this study were composed of human SK-OV-3 ovarian cancer or MDA-MB-468 breast cancer cells which homogeneously and highly express HER2 or EGFR, respectively." (PMID 38711454, 2024). "We ascertained EGFR expression and cyclin A, cyclin E, and CDK2 levels in breast cancers by bulk, single-cell, and spatial transcriptomic analyses." (PMID 38772416, 2024). "Although both breast cancer and gastric cancer highly express HER2, gastric cancer expresses higher level of EGFR than breast cancer." (PMID 38982548, 2024). "Immunoblot further verified that neratinib effectively downregulated Cyclin D1, CDK4 and EGFR by inhibiting the HER2 pathway, thus enhancing the efficacy of CDK4/6 inhibitor combined with endocrine therapy in HR+/HER2-low breast cancer (P < 0.01)." (PMID 39730704, 2024). "Specifically, in breast cancer cells, ANO1, epidermal growth factor receptor, and signal transducer and transcriptional activator 3 form a positive feedback pathway that promotes cancer cell proliferation and growth." (PMID 38352864, 2024). "Raman signals of pre-blocked groups decreased by about 30% compared with the unblocked group, indicating that the nanomaterial is sensitive and specific to distinguish breast cancer with different expression levels of PDL1 and EGFR." (PMID 38918821, 2024). "Combining the results of network pharmacology with other bioinformatics databases suggests that myrrh’s active components exert anti-cancer effects by regulating genes involved in breast cancer pathogenesis, particularly PTGS2, EGFR, ESR2, MMP2, and JUN." (PMID 39707884, 2024). "Among them, EGFR, MAPK1, MAPK3, PTGS2, and ESR1 were specifically evaluated for breast cancer treatment." (PMID 38794187, 2024).
breast carcinoma (continued). "Gastric cancer cell line NCI-N87 and breast cancer cell line SKRB3 and BT-474 are representative of gastric cancer and breast cancer regarding HER2, HER3 and EGFR expression status." (PMID 38982548, 2024). "Favouring signalling via this mechanism, lipid rafts have been shown to provide a platform for EGFR and c-SRC interaction in breast cancer cells." (PMID 39165974, 2024). "Treatment with APS results in a significant decrease in EGFR levels and a marked increase in ANXA1 levels in breast cancer cells." (PMID 38794206, 2024). "Subsequent in vitro investigations revealed a significant reduction in the expression levels of p-EGFR, p-AKT, and p-ERK1/2 proteins, underscoring the pivotal functions of EGFR, PI3K/Akt, and MAPK signaling pathways in SP’s anti-breast cancer properties." (PMID 39057437, 2024). "Pyrotinib is an inhibitor of EGFR (ERBB1) and HER2/4 (ERBB2/4), which is approved for the treatment of breast cancer in China." (PMID 39201509, 2024). "Instead, HER2-mediated signaling is activated through heterodimerization with ligand-activated EGFR or ERBB3, or through homodimerization when HER2 is highly expressed, which is often observed in breast cancer patients." (PMID 39596465, 2024). "Specifically, in breast cancer, STAMBP knockdown inhibited cell mobility and invasion by compromising EGFR/MAPK signaling pathway activation and inducing the degradation of actin-binding proteins." (PMID 38594742, 2024). "In breast cancer cell lines, HER3 expression was shown to be essential for maintaining cell viability, whereas EGFR was dispensable." (PMID 39020378, 2024). "In MDA-MB-231, a breast cancer cell line with moderate levels of ZNRF3/RNF43, overexpression of either ZNRF3 or RNF43 substantially reduced EGFR protein levels." (PMID 38260423, 2024). "In the present study, epidermal growth factor receptor (EGFR), Aromatase, and PI3K alpha were chosen as targets as they are key proteins involved in disease progression and metabolic processes in breast cancer." (PMID 40066125, 2024). "Lapatinib, on the other hand, is a reversible and potent dual EGFR and HER2 inhibitor that is approved in combination with capecitabine for the treatment of breast cancer, one of the most common and deadly cancers in women." (PMID 39780846, 2024). "SP was finally reported to suppress MCF-7 cell growth and induce apoptosis by modulating the PI3K/AKT/EGFR and MAPK signaling pathways suggesting EGFR as a potential target of SP in breast cancer (BC) treatment." (PMID 39057437, 2024). "CDDO-Im has been shown to be a potent inhibitor of the epidermal growth factor receptor (EGFR) and STAT3/SRY-Box transcription factor 2 (Sox-2) signaling pathways in tumor-inducing macrophage (TIM) cells, which stimulate breast cancer growth and metastasis." (PMID 39064870, 2024). "Multiple transactivations between GPCRs and EGFR that induce oncogenic pathways are described, such as GPR30 and EGFR, to activate the oncogenic MAPK and PI3K/Akt pathways or the protease-activated receptor 1 and EGFR in breast cancer." (PMID 38612509, 2024). "These include PTGS2, EGFR, ESR2, MMP2, JUN, and HSP90AB1, which all revealed the highest mRNA expression level in the basal breast cancer subtype, thus proposing a potential similar engagement of these genes in the pathogenesis of the basal subtype." (PMID 39707884, 2024). "GABAAR π has been shown to stimulate breast cancer cell invasion through the ERK1/2 pathway and it also interacts with EGFR and sustains EGFR expression in TNBC." (PMID 39469630, 2024). "Lapatinib treatment inhibits activation of the MEK/ERK signaling pathway, radiosensitising EGFR+ and HER2+ breast cancer cells." (PMID 38088952, 2024). "Dual inhibitors of HER2 and EGFR, such as lapatinib, have shown significant efficacy for the therapy of HER2-positive breast cancer." (PMID 39403185, 2024).
breast carcinoma (continued). "The diagnosis-specific GPA score adds EGFR, BRAF, hemoglobin, HER2, and breast cancer subtype as factors that enhance the scoring accuracy for the respective tumors." (PMID 38668035, 2024). "For this purpose, we used the Gene expression-based Outcome for Breast Cancer Online (GOBO) dataset that contains data about 1881 breast cancer patients to produce a gene set composed of PTGS2/ESR2/EGFR/JUN/ MMP2 genes’ signature." (PMID 39707884, 2024). "This dual regulatory capacity of UCHL1, affecting both the mRNA and protein levels of EGFR, distinguishes UCHL1 from other DUBs in the context of breast cancer." (PMID 38468288, 2024). "In the MDA-MB-231 breast cancer cell line (ER−/PR−/HER2−, EGFR+), curcumin reduced ERK phosphorylation, while apigenin inhibited tyrosine phosphorylation of HER2 and reduced the expression of phospho-JAK1 and phospho-STAT3." (PMID 39519572, 2024). "Following this, a gene similar to EGFR, which is known as the human epidermal growth factor receptor 2 (HER2) gene, was found to be amplified in a human breast cancer cell line." (PMID 38601214, 2024). "Previous studies have shown that EGFR from tumor cells can regulate the recruitment of macrophages by increasing CCL2 expression in glioblastoma and breast cancer." (PMID 38515213, 2024). "It serves as a crucial diagnostic marker and therapeutic target for various tumors, especially EGFR and HER2 altering in lung cancer and HER2 altering in breast cancer." (PMID 39404930, 2024). "The primary pathways involved in stimulating cell growth in breast cancer are the ER and HER2/EGFR signaling pathways." (PMID 39051060, 2024). "The current analysis further certifies the decisive engrossment of PTGS2/ESR2/EGFR/JUN/MMP2 genes’ signature and some interactor proteins in promoting breast cancer development." (PMID 39707884, 2024). "Membrane raft-localized EGFR expression is altered in MCF-7 and MDA-MB-231 cells by cholesterol metabolite 4-cholesten-3-one, which decreases breast cancer cell viability, reduces lipogenesis, and enhances liver X receptor-dependent cholesterol transporters." (PMID 39329960, 2024). "Tspan1 and Tspan15 activate the PI3K/AKT and EGFR/MAPK/ERK pathways, respectively, leading to enhanced proliferation in cholangiocarcinoma and breast cancer." (PMID 38649381, 2024). "A mouse model study has shown that EGFR/Stat3 and TGF-β/Smad signaling is required for autophagy functions in two distinct breast cancer stem-like cells CSCs (ALDH+ and CD29high/CD61+, respectively)." (PMID 39201332, 2024). "This reveals a potential mechanism by which the EGFR-AKT-TSPAN8-STAT3 axis negatively affects prognosis and treatment resistance in breast cancer and other malignancies." (PMID 39769140, 2024). "The interplay between GPER and EGFR suggests that a therapeutic approach involving a combination of GPER and EGFR inhibitors holds promise for combating breast cancer." (PMID 38476263, 2024). "After treating breast cancer cells with a macrophage-conditioned medium for 24 h, we observed a down-regulation of ER and PR, coupled with an up-regulation of HER2 and EGFR." (PMID 38339428, 2024). "Upon downregulation of Spry functions, e.g., when the Spry genes are knocked out in the mutant mammary glands or their functions are otherwise silenced in breast cancer, multiple pathways of RTK signaling, especially downstream of EGFR and IGFR, are increased." (PMID 38600092, 2024). "The dual tyrosine kinase inhibitor lapatinib, which targets EGFR and HER2, has been approved by the FDA for HER2-positive breast cancer." (PMID 38542136, 2024).